NDRG2 (NDRG family member 2)
Diseases named in the same sentence as NDRG2 in open-access papers (continued):
Sharing a sentence is not in itself a finding about the gene and the disease.
glioma (19 papers, 2007 to 2026). A benign or malignant brain and spinal cord tumor that arises from glial cells (astrocytes, oligodendrocytes, ependymal cells). "As the grade of the glioma increases, NDRG2 expression decreases, which is associated with a worse overall prognosis." (PMID 41596413, 2026). "The NDRG2 has been confirmed to be involved in cell growth and differentiation, meanwhile, NDRG2 expression in high-grade gliomas has been shown to associate with survival." (PMID 24146910, 2013). "Furthermore, NDRG2 induces the ubiquitination and degradation of PC under glutamine deficiency, and NDRG2 loss leads to increased PC and PC-dependent anaplerosis and glioma tumorigenesis." (PMID 35877430, 2022). "The main mechanism underlying NDRG2 silencing in gliomas remains unknown." (PMID 36132155, 2022). "This synergistic dysregulation appears to weaken tumour-suppressive mechanisms, highlighting NDRG2 as a potential prognostic biomarker and therapeutic target in high-grade gliomas." (PMID 41179304, 2025). "Another study reported NDRG2 expression as an independent prognostic factor for overall survival in glioma patients." (PMID 31485792, 2019). "Three other studies confirmed the finding that NDRG2 expression is lower in gliomas due to NDRG2 promoter methylation." (PMID 31485792, 2019). "NDRG2 has also been found as a candidate tumor suppressor gene in glioma as NDRG2 expression was markedly reduced in grade IV glioma tissues (n = 27)." (PMID 31485792, 2019). "NDRG2 expression was investigated in grade I–IV glioma tissue samples (n = 316) and was found to be decreased in more aggressive glioma grades compared with healthy controls." (PMID 31485792, 2019). "The antiproliferative function of NDRG2 was also observed in C6-originated astrocytes (differentiated C6 glioma cells)." (PMID 31485792, 2019). "In this study, we investigated the role of NDRG2 in cellular apoptosis induced by oxygen-glucose deprivation (OGD) in IL-6-differentiated C6 glioma cells." (PMID 23451161, 2013). "To investigate the role of NDRG2 in astrocytes, we employed the IL-6-differentiated C6 glioma cells as normal astrocytes." (PMID 23451161, 2013). "The results of these authors revealed decreased NDRG2 expression in approximately 60% of gliomas vs. the expression levels in normal brain tissue." (PMID 20804549, 2010). "NDRG2 expression levels in gliomas and meningiomas were significantly attenuated in high-grade compared to low-grade tumors." (PMID 17935612, 2007). "It has recently been shown that overexpression of NDRG2 in a glioblastoma cell-line inhibits cell proliferation and that NDRG2 expression correlates positively with survival in high-grade glioma." (PMID 17935612, 2007). "Furthermore, the hypermethylation of the NDRG2 promoter has been shown to be an early event in glioma development, contributing to the aggressive nature of these tumors." (PMID 41596413, 2026). "Moreover, the increase in NDRG2 expression within cancer cells can be related to improved prognosis in gastric cancer, high-grade glioma and hepatocellular carcinomas." (PMID 32345304, 2020). "In addition, the methylation rate of the NDRG2 promoter was with 46.3% in glioma tissue significantly different from the 18.2% in normal tissue." (PMID 31485792, 2019). "The methylation rate of the NDRG2 promoter region is significantly higher in glioma, HCC, meningioma, and gastric carcinoma tissues compared with adjacent normal tissues, which may down-regulate NDRG2." (PMID 26506239, 2016). "Although the function of NDRG2 is currently unknown, high NDRG2 expression correlates with improved prognosis in high-grade gliomas, gastric cancer and hepatocellular carcinomas." (PMID 21226903, 2011). "Furthermore, elevated expression of NDRG2 in tumors correlates with an improved prognosis in gastric cancer, high-grade glioma and hepatocellular carcinomas." (PMID 21226903, 2011).
glioma (continued). "In addition, higher expression of NDRG2 mRNA correlated with clinically less aggressive tumors in meningiomas and NDRG2 expression in high-grade gliomas was positively correlated with survival." (PMID 20673333, 2010). "Furthermore, NDRG2 was identified as a gene whose expression in high-grade gliomas was positively correlated with survival." (PMID 17935612, 2007). "Although the function of NDRG2 is unknown, high NDRG2 expression correlates with improved prognosis in high-grade gliomas." (PMID 17935612, 2007). "There is also debate on whether NDRG2 gene activity reflects the survival of glioma patient." (PMID 36132155, 2022). "In contrast to NDRG2, the studies regarding expression of NDRG4 in glioma show conflicting outcomes." (PMID 31485792, 2019). "After nearly 17 years of work, our laboratory and other groups have clearly shown that NDRG2 expression is decreased in multiple tumor tissues, including CRC, glioma, and hepatoma." (PMID 29445150, 2018). "Furthermore, in the NDRG family, NDRG2 acts in a tumor-suppressive manner similar to NDRG1, while NDRG4 is lowly expressed in gliomas and is considered as a poor prognostic factor." (PMID 35448004, 2022). "Tepel and colleagues observed decreased NDRG2 protein and mRNA expression in grade IV gliomas compared with grade II and grade III gliomas (n = 67) and observed hypermethylation in 62% of grade IV gliomas (n = 34)." (PMID 31485792, 2019). "Moreover, NDRG1, NDRG2, and NDRG4 are all involved in cancers of the nervous system, such as glioma, neuroblastoma, or meningioma." (PMID 31485792, 2019). "Glioma tumor grade is significantly negative with NDRG2 expression level." (PMID 26506239, 2016).
colon carcinoma (17 papers, 2007 to 2025). "Here, we investigated the outcome of NDRG2 overexpression on proliferation, invasion, migration, and MMP-9 activity in HCT116 cells, a model of colon cancer with a KRAS mutation." (PMID 29399558, 2017). "In SW620 colon carcinoma cells, the induction of NDRG2 decreases c-Jun phosphorylation at Ser63, which is followed by the attenuation of the transcriptional activator AP-1 (activator protein-1)." (PMID 26506239, 2016). "In renal cell carcinoma and colon cancer cells, NDRG2 can recover E-cadherin expression, and this effect can be reversed by NDRG2 siRNA." (PMID 26506239, 2016). "Our previous research indicated that NDRG2 was expressed widely in normal tissues, and decreased in colon tumor and other types of tumor tissues." (PMID 26317652, 2015). "Transfection of human glioblastoma with Ndrg2 cDNA reduced cell proliferation while low NDRG2 has been detected in colon carcinoma." (PMID 24816982, 2014). "In our previous study using colon carcinoma cells, NDRG2 modulated the cell cycle via phosphorylation of c-Jun and the down-regulation of AP-1 and cyclin D1." (PMID 25061501, 2014). "NDRG2 expression was deficient in many kinds of tumors, such as melanoma, glioblastoma, thyroid cancer, colon cancer, and pancreatic cancer, and NDRG2 was able to inhibit proliferation of certain tumor cells." (PMID 23307246, 2013). "Further studies in colon cancer and other tumors revealed that NDRG2 level was correlated with tumor differentiation and stage." (PMID 23307246, 2013). "In studies of Norwegian authors, it was demonstrated that mRNA level of NDRG2 gene was significantly lower in colon cancer tissue than in normal tissues." (PMID 20804549, 2010). "Third, to evaluate the methylation status of PRDX6 an NDRG2 genes in normal and cancer tissues, as well as in colon cancer cell lines, bisulphite sequencing analysis was used." (PMID 19257893, 2009). "The MSP assay was used to check for NDRG2 methylation status in 30 primary colon tumour tissues compared to normal colonic mucosal samples." (PMID 19257893, 2009). "In the NDRG2 gene a significant methylation status either in colon cancer cell lines and in tumour tissue compared to normal tissue was observed." (PMID 19257893, 2009). "Preliminary experiments using a Cancer Profiling Array indicated that expression of NDRG2 mRNA was reduced in 9 out of 10 colonic tumors." (PMID 17935612, 2007). "In the present study we demonstrated that NDRG2 mRNA expression levels were lower in colonic tumors than in normal colon tissue from the same individual." (PMID 17935612, 2007). "Reports from cancer studies demonstrated that NDRG2 inhibits c-Myc expression by suppressing the expression of β-catenin and reduces c-Jun phosphorylation and cyclin D1 expression resulting in suppression of cell proliferation in human colon carcinoma cells." (PMID 32433643, 2020). "Emerging evidence demonstrates the involvement of NDRG2 in colon cancer." (PMID 29399558, 2017). "For example, NDRG2, a kinase downstream of the mTOR/SGK pathway and a tumor suppressor that mediates apoptosis, and EMD, a nuclear membrane protein phosphorylated by Src, both preferentially bind HNF4α1 and have been negatively associated with colon cancer." (PMID 27166517, 2016). "Moreover, NDRG2 also inhibited the growth, proliferation and invasion of colon tumor cells and other types of tumor cells." (PMID 26317652, 2015). "Furthermore, NDRG2 attenuated tumor cell proliferation via the down-regulation of activator protein 1 (AP-1) activity in human colon carcinoma cells." (PMID 25061501, 2014). "In 2006 it was shown that the Myc oncoprotein could interact with the NDRG2 promoter via Miz-1 and that the level of Myc is inversely correlated with the level of NDRG2 in colon cancer cell-lines undergoing differentiation." (PMID 21226903, 2011).
colon carcinoma (continued). "Kim and colleagues demonstrated that NDRG2 expression decreases with increasing tumor stage in colon carcinoma, indicating that this may be an excellent marker for molecular staging." (PMID 20860831, 2010). "In conclusion, we showed that NDRG2 expression is frequently suppressed in colon cancer cell lines in conjunction with aberrant DNA methylation, and that the loss of expression of this gene could be related to advanced colon tumour stage." (PMID 19257893, 2009). "The aim of this study has been to examine NDRG2 mRNA expression in colon cancer." (PMID 17935612, 2007). "Expression analysis of NDRG2 in colon cancer using a Cancer Profiling Array." (PMID 17935612, 2007). "In this study, we analyzed NDRG2 promoter methylation using PSQ technique, because the sequence, reported to be a target of aberrant methylation in colon cancer and used in our MSP analysis, was found unmethylated in all meningioma samples analyzed." (PMID 25648363, 2015).
hepatocellular carcinoma (17 papers, 2010 to 2026). A malignant tumor that arises from hepatocytes. "In addition, NDRG2 expression had an inverse association with LDHA expression and NDRG2 inhibited LDHA expression in hepatocellular carcinoma." (PMID 31523182, 2019). "More importantly, NDRG2 is closely related to the occurrence and development of hepatocellular carcinoma." (PMID 31523182, 2019). "In hepatocellular carcinoma cells with active metabolism, NDRG2 also inhibits aerobic glycolysis, cell growth, cell proliferation and mediates the inhibitory effect of gemcitabine on aerobic glycolysis." (PMID 31523182, 2019). "Although one recent study showed that Dp44mT inhibited the invasion and metastasis in hepatocellular carcinoma cells by increasing NDRG2 expression, our result shows that treatment of iron chelators did not affect NDRG2 expression in SAS and OECM-1 cells." (PMID 27589737, 2016). "NDRG2 modulates the adhesion and invasion of hepatocellular carcinoma cells through regulating CD24 expression." (PMID 25889839, 2015). "NDRG2 mRNA was induced by non-steroidal FXR agonists in livers of mice and the magnitude of induction of NDRG2 mRNA in three different human hepatoma cell lines was increased when ectopically expressing human FXR." (PMID 23056173, 2012). "Such a reduction of NDRG2 mRNA has been reported in tumor tissue compared to adjacent “normal” tissue of patients with hepatocellular carcinoma." (PMID 23056173, 2012). "We show that FXR, when activated by a non-steroidal agonist, induced the transcription of the liver tumor suppressor candidate NDRG2 in mouse liver and three different human hepatoma cell lines." (PMID 23056173, 2012). "Furthermore, NDRG2 expression was shown to be associated with MMP downregulation in clear cell renal cell carcinoma (CCRCC) and hepatocellular carcinoma (HCC)." (PMID 34685629, 2021). "Moreover, NDRG2 also inhibited the activation of fatty acid oxidation under glucose limitation in hepatoma cells." (PMID 31523182, 2019). "However, little is known about glycolytic function and therapeutic value of NDRG2 in hepatocellular carcinoma (HCC)." (PMID 31523182, 2019). "It is therefore tempting to speculate, that the downregulation of Ndrg2 mRNA in FXR−/− mice might contribute to the time dependent development of hepatocellular carcinoma in these mice." (PMID 23056173, 2012). "Here we showed that hepatocellular carcinoma (HCC) cell lines with high metastatic potential had low levels of NDRG2." (PMID 25261367, 2014). "NDRG2 has been demonstrated to be a candidate suppressor of liver cancer and metastasis and in particular, stable overexpression of NDRG2 was shown to suppress the invasion and migration of the highly invasive hepatoma cell line SK-Hep-1 in an experimental xenograft model in the mouse." (PMID 23056173, 2012). "It is reported that NDRG2 could antagonize transforming growth factorβ1-mediated tumor cell invasion by specifically down-regulating the expression of matrix metalloproteinase 2 and laminin 332 pathway components, with concomitant suppression of Rho GTPase activity in hepatocellular carcinomas." (PMID 24146910, 2013). "Here we show that NDRG2 is a direct transcriptional target of FXR in mouse liver and human hepatoma cell lines." (PMID 23056173, 2012). "NDRG2 overexpression inhibits the expression of MMP2 and MMP9 in clear cell renal cell carcinoma (CCRCC) and hepatocellular carcinoma (HCC)." (PMID 26506239, 2016). "In humans, both, NDRG2 and FXR mRNA's are reduced in primary hepatocellular carcinoma samples of different tumor stages compared to normal human liver or non-HCC liver diseased human liver." (PMID 23056173, 2012). "We therefore analyzed the expression of genes including FXR and NDRG2 in a commercially available cDNA panel derived from liver specimens from healthy individuals and liver specimens from patients with stage I, II, IIIA and IV hepatocellular carcinoma as well as non-malignant liver diseases." (PMID 23056173, 2012).
meningioma (17 papers, 2007 to 2025). A generally slow growing tumor attached to the dura mater. "Relatively few gene-level alterations, including CDKN2A/B, TERT, and NDRG2 (N-myc downstream-regulated gene family member 2), have been strongly associated with the malignant progression of meningioma." (PMID 36836440, 2023). "Earlier, the downregulation of this gene was described in a subset of lower-grade meningiomas, including atypical meningiomas with clinically aggressive behavior, which was associated with hypermethylation of the NDRG2 promoter." (PMID 25648363, 2015). "Despite the methylation of NDRG2 in the majority of meningiomas, it cannot be considered as a diagnostic biomarker because its methylation level is only slightly elevated in comparison to non-cancerous brain tissue." (PMID 25648363, 2015). "Another study confirmed that ~40% of downregulated genes were located at 1p and 14q in anaplastic meningiomas, whereas the 14q11.2 gene NDRG2 was consistently downregulated in grade III meningiomas." (PMID 37654657, 2023). "Recurrent meningiomas displayed a statistically significant reduction in NDRG2 mRNA levels, when compared with primary meningiomas." (PMID 31485792, 2019). "Loss of NDRG2 mRNA and protein levels was found in anaplastic (grade III) meningiomas and in a clinically aggressive subset of atypical (grade II) meningiomas, most likely caused by NDRG2 CpG promoter methylation." (PMID 31485792, 2019). "The analysis of five CpG sites in NDRG2 promoter revealed methylation in a large subset of meningiomas." (PMID 25648363, 2015). "The sequence of NDRG2 chosen for PSQ analysis was found methylated in the majority of meningiomas; however, the methylation level was only slightly elevated as compared to non-cancerous brain." (PMID 25648363, 2015). "Recently, significant differences in the expression of NDRG2 gene were reported between primary and recurrent meningioma groups, and benign and atypical meningiomas." (PMID 25648363, 2015). "Accordingly, NDRG2 was found to be frequently downregulated at both the transcript and the protein levels in anaplastic meningiomas and in a subset of lower-grade and atypical cases with an aggressive clinical behavior, as well as in recurrent meningiomas." (PMID 25965831, 2015). "In summary, this study provided evidence that p14ARF, RASSF1A, p15INK4B (CDKN2B), RUNX3, GATA6, p16INK4A (CDKN2A), NDRG2 and to lesser extent ATM and RARβ promoter methylation are associated with the development of meningiomas." (PMID 25648363, 2015). "Recent reports have shown that NDRG2 was differentially expressed in tumour and normal tissues, and NDRG2 expression was consistently down-regulated in grade Ш meningioma at both the transcriptional and translational levels." (PMID 23800335, 2013). "Ndrg2 is a candidate tumor suppressor gene on chromosome 14q that is inactivated during meningioma progression." (PMID 20098702, 2010). "Furthermore, NDRG2 gene expression was found to be significantly decreased by 3.7-fold in atypical (grade II) meningiomas when compared with benign (grade I) meningiomas." (PMID 31485792, 2019). "Combining these findings, we hypothesize that NDRG2 should be considered a tumor suppressor gene in meningiomas." (PMID 31485792, 2019). "NDRG2 was found to be commonly inactivated in meningioma progression." (PMID 27429002, 2016). "Thus, the results of our study confirm that mild NDRG2 methylation is a common event in meningioma formation, but clinical application of this observation seems to be limited." (PMID 25648363, 2015). "In meningiomas, higher expression of NDRG2 mRNA correlated with clinically less aggressive tumors." (PMID 17935612, 2007). "Furthermore, NDRG2 expression was lower in grade II meningiomas compared with grade I lesions." (PMID 27007654, 2016).
meningioma (continued). "We determined expression of the proteins merlin, NDRG2, ERBB2, and c-MYC in meningiomas using immunohistochemistry and assessed relationships between protein expression and gender, age, tumor grade, and recurrence or regrowth." (PMID 27007654, 2016). "We have investigated the expression of merlin, NDRG2, ERBB2, and c-MYC in patient meningioma specimens using immunohistochemistry (IHC)." (PMID 27007654, 2016). "The aim of this study was to evaluate the methylation status of 12 cancer-related genes, namely ERCC1, hMLH1, ATM, CDKN2B (p15INK4B), p14ARF, CDKN2A (p16INK4A), RASSF1A, RUNX3, GATA6, NDRG2, PTEN, and RARβ, in 44 meningioma samples of WHO grade I and II." (PMID 25648363, 2015). "This study revealed the identification of phosphorylated sites of several proteins that were found to play a role in meningioma pathobiology by several studies including EPB41L2, NDRG2, SPTB, MAGED2, MXRA7, and nearly 51 Kinases which were also mapped further through Kinome Analysis." (PMID 32974197, 2020). "Expression of merlin, NDRG2, ERBB2, and c-MYC was not significantly different statistically with relation to gender, age, or meningioma recurrence or regrowth." (PMID 27007654, 2016).